CXCL10 (C-X-C motif chemokine ligand 10)
Diseases named in the same sentence as CXCL10 in open-access papers (continued):
Sharing a sentence is not in itself a finding about the gene and the disease.
type 1 diabetes (47 papers, 2006 to 2025). "Type I diabetes (T1D) is associated with an increase in Th1-associated chemokines such as IP-10 (CXCL10)." (PMID 36286054, 2022). "In animal models of type 1 diabetes, pancreatic insulitis was associated with CXCL10 production and inhibition of the CXCL10/CXCR3 axis prevented development of autoimmune diabetes." (PMID 36059840, 2022). "In turn, in case children at the age of 6 months, n-6 LA and AA were directly associated with cytokines (IL-6, IL-9, and CXCL10), which have been previously linked to pre-clinical and clinical type 1 diabetes." (PMID 35693790, 2022). "We observed that in case children, several SFAs and CLA were associated with many immunological markers [CXCL10 (IP-10), IL-6, IL-9, IL-17, and CM-CSF] that have been linked to the development of type 1 diabetes." (PMID 35693790, 2022). "In cases, SFAs were associated with several immunological markers (CXCL10, IL-6, IL-9, IL-17, and CM-CSF) previously linked to the type 1 diabetes disease process." (PMID 35693790, 2022). "Still another CXCL10 polymorphic variant, CXCL10 rs8878 TT, was found to reduce the risk of type 1 diabetes." (PMID 23150742, 2012). "Another study reported increased expression of several genes typically induced by type I and II IFNs including STAT1, CXCL10 and HLA-I in islet tissue of living individuals with recently diagnosed type 1 diabetes." (PMID 37113489, 2023). "Serum CXCL10 levels were significantly higher in patients with acute‐onset type 1 diabetes (n = 27) or slowly progressive type 1 diabetes (n = 23) than in non‐diabetic controls (n = 8; age 35 ± 12 years)." (PMID 30919585, 2019). "In a longitudinal study of children enrolled at diagnosis of type 1 diabetes, significantly higher CXCL10 levels were found in these participants compared with healthy control individuals." (PMID 29881878, 2018). "CXCL10 is the most abundant chemokine expressed in infiltrated PA in mouse models, including InsHA, as well as in type 1 diabetic patients, and this chemokine contributes to T cell recruitment." (PMID 29904378, 2018). "In agreement with findings in other chronic inflammatory conditions, such as type I diabetes, systemic sclerosis, and autoimmune thyroiditis, we found that the CXCL10 serum levels are significantly increased in untreated CD patients." (PMID 24586509, 2014). "First, we review recent findings that blockade of IL-10/IL-10R interaction can resolve chronic viral infection and second, we reflect on how neutralization of the chemokine CXCL10 can abrogate virus-induced type 1 diabetes." (PMID 17162375, 2006). "Interestingly, our EC model showed an increase in CXCL10, ICAM1, IL-6, and MIF, which are associated with type I diabetes development." (PMID 31835296, 2019). "In line with these earlier reports, we found increased serum concentrations of CXCL10 in adults with newly diagnosed type 1 diabetes and slightly lower levels in adults with long-standing type 1 diabetes (but elevated compared with healthy control individuals)." (PMID 29881878, 2018). "Serum concentrations of CXCL10 are known to be elevated in individuals with recent-onset type 1 diabetes, although there has been one report of decreased CXCL10 levels in children with type 1 diabetes." (PMID 29881878, 2018). "Alterations in IFN-stimulated gene patterns (including in Ifit, Mx2, Cxcl10) and/or in Jak/STAT activity, a main IFN-dependent pathway, cause a failure in immunological tolerance resulting in T cell-mediated autoimmune pathologies (e.g., type I diabetes)." (PMID 27256343, 2016). "miRNA-16–5p, expressed at lower levels in type 1 diabetes mellitus (T1DM) patients, can inhibit high-glucose-induced pancreatic β-cell apoptosis by targeting CXCL10." (PMID 36818396, 2023).
type 1 diabetes (continued). "However, we believe that current study is informative considering that few studies have investigated the association among islet autoantibody status, β‐cell function and serum CXCL10 levels in patients with acute‐onset type 1 diabetes or slowly progressive type 1 diabetes." (PMID 30919585, 2019). "The persistence of high serum CXCL10 levels indicates that prolonged disease activity might accelerate functional β‐cell impairment in patients with acute‐onset type 1 diabetes or slowly progressive type 1 diabetes." (PMID 30919585, 2019). "Another study demonstrated that CXCL10 levels increase over time in at-risk individuals, peaking as they become seropositive for islet autoantibodies, irrespective of further progression to clinical type 1 diabetes." (PMID 29881878, 2018). "The simultaneous upregulation of chemokines that promote (CXCL10, CXCL9) and protect against (CCL17, CCL22) type 1 diabetes suggests a complex immune response to PET microplastics." (PMID 40597598, 2025). "CXCL10 and its cognate receptor CXCR3 have been previously identified as potential therapeutic targets in type 1 diabetes, orchestrating the migration of islet-specific T cells into the pancreas." (PMID 37458220, 2023). "C-X-C motif chemokine 10 (CXCL10/IP10), which is induced by IFN-γ, has an important role in recruiting activated T cells into the islets in type 1 diabetes." (PMID 27110066, 2016). "In transgenic mice, the overexpression of CXCL10 in the pancreas induces a rapid recruitment of effector CD4+ and CD8+ T cells and accelerates the progression of type I diabetes." (PMID 24586509, 2014). "Moreover, CXCL9, in conjunction with CXCL10, also changes the mass and function of β-cells, and deletion of CXCR3 in mice delays the onset of type 1 diabetes." (PMID 40597598, 2025). "Evidence from both type 1 diabetes animal models and human pancreatic organ donors with recent-onset type 1 diabetes identified CXCL9 and CXCL10 as key chemokines that induce the attraction of autoreactive T cells bearing the corresponding chemokine receptor CXCR3 to pancreatic islets." (PMID 37458220, 2023). "Combining anti-CD3 treatment with the blockade of the CXCR3/CXCL10 axis using ACT-777991, a CXCR3 antagonist, further preserves B-cell damage and synergistically increases persistent remission in experimental models of type 1 diabetes." (PMID 37458220, 2023). "Future studies will focus on investigating the ability of B cells from individuals with type 1 diabetes to migrate in response to physiological levels of CXCL10 and CXCL11, in the presence and absence of BAFF." (PMID 29881878, 2018). "A disease-relevant synergy may therefore exist in the setting of type 1 diabetes among raised levels of BAFF, CXCL10 and CXCL11." (PMID 29881878, 2018).
Arthritis (45 papers, 2006 to 2026). Inflammation of a joint. "CXCR3 ligands such as CXCL9 and CXCL10 also cause bystander T cell migration in the case of Lyme disease, causing inflammation in joints and arthritis." (PMID 36951943, 2023). "A pathogenic role for CXCL10 in arthritis was previously demonstrated in RA patients as well as in mouse models." (PMID 35734167, 2022). "From DisGeNET: Adenitis and Arthritis, Infectious, are associated with the gene CXCL10." (PMID 39766770, 2024). "Previously, we reported that arthritis was associated with the upregulation of IP-10/CXCL-10." (PMID 31036046, 2019). "Blocking CXCL10 rescued PsA-like phenotypes (skin and joint inflammation), as indicated by attenuated epidermal hyperplasia, inflammatory infiltration, enthesitis, cartilage damage, and bone erosions." (PMID 40471688, 2025). "To validate these observations in vivo, we used Ube2d1 knockout mice, which exhibit impaired CXCL10 induction and attenuated arthritis severity, highlighting the pivotal role of Ube2d1 in driving this inflammatory program." (PMID 42004226, 2025). "Clinically, elevated CXCL9/CXCL10 levels have been detected in the serum of patients with ICI-induced arthritis and in lesional skin biopsies from those with immunotherapy-related dermatitis, directly linking this chemokine to irAE pathogenesis across organs." (PMID 40722787, 2025). "CXCL10 KO mice showed mild arthritis in CAIA model through the inhibition of macrophage and T-cell migration into the synovium." (PMID 36860872, 2023). "Monoclonal bispecific antibodies against TNF-α and CXCL10 attenuated arthritis symptoms in mice by inhibiting CXCL10-mediated CD8+ T cell migration." (PMID 36860872, 2023). "In humans, severe CHIKV arthritis is associated with elevated serum cytokine/chemokine levels, such as IL-1β, IL-6, TNF-α, CXCL10, etc.." (PMID 36377866, 2022). "In 2020, the same group demonstrated that CXCL10 levels drop following the development of arthritis, with the authors suggesting that their findings warrant further investigation into the predictive value of CXCL10 in PsA diagnosis." (PMID 35368374, 2022). "The use of an anti-CXCL10 antibody blocks osteoclast differentiation, thereby preventing the progression of arthritis in mice that present with fewer histological sequelae than controls." (PMID 33817614, 2021). "In summary, our results demonstrate that CXCL10 signaling contributes to alphaviral replication and the pathogenesis of alphavirus-induced arthritis." (PMID 33147869, 2020). "In an exploratory analysis, patients with SLE with arthritis (according to the ACR criteria) had increased levels of both CXCL10 and CXCL13." (PMID 30092845, 2018). "Baseline IL-17 and CXCL10 expression was especially prominent in cases of ICI-induced arthritis, whereas TGFβ1 was linked to both ICI-induced arthritis and colitis." (PMID 30400835, 2018). "Taken together, these results demonstrate that the clinically observed amelioration of arthritis in Cxcl10–/– and Cxcr3–/– mice was reflected by suppression of joint inflammation and destruction of bone and cartilage." (PMID 28724396, 2017). "Using the flow cytometry-based, predesigned Human Chemokine CBA Kit, we detected higher levels of CCL2, CCL3, CCL4, CCL5, CXCL9, and CXCL10 in arthritis than in CTRL plasma." (PMID 28619088, 2017). "As mentioned in the introduction, the studies demonstrated that the expression of CXCL10 and CXCR3 was increased in the collagen-induced arthritis model, and neutralizing anti-CXCL10 antibodies ameliorated disease manifestation in these models." (PMID 24939012, 2014). "Focusing on the links between skin lesions and arthritis, we utilized these Spry1-cKO mice as a mouse model for PsA and found that SPRY1-deficient keratinocytes produced excessive CXCL10, which bound to CD14 to promote the proinflammatory response of periarticular CD14hi macrophages." (PMID 40471688, 2025).
Arthritis (continued). "It was also shown that during the evolution to arthritis the serum level of CXCL10 diminished: a larger negative change was associated with a higher risk of PsA." (PMID 34127053, 2021). "Indeed, it has been reported also that CXCL9 and CXCL10 act as macrophage chemoattractants in arthritis, chronic cardiac inflammation, and cancer, thus implicating these chemokines in inflammatory disease." (PMID 33510341, 2021). "In addition, anti-CXCL10 antibodies suppress bone destruction in a collagen-induced arthritis model." (PMID 33510341, 2021). "CXCL10 has been shown to be involved in the development of arthritis." (PMID 33519292, 2020). "Furthermore, previous studies have shown that pharmacologic blockade of CXCL10 signaling inhibits arthritis progression in animal models, mainly via inhibition of T-cell migration into the joint." (PMID 28724396, 2017). "Cxcl10–/– and Cxcr3–/– mice developed less severe arthritis than WT mice." (PMID 28724396, 2017). "This is in contrast to arthritis-susceptible B6 IL10−/− mice, where previously published data show that in addition to upregulation in IL-1β, IL-6, Cxcl1 and Cxcl2, IFNγ and Cxcl10 are upregulated 16-fold and 141-fold at 2 weeks, and 22-fold and 189-fold at 4 weeks, respectively." (PMID 24967703, 2014). "Indeed, recent studies that either targeted Cxcl10 or its receptor CXCR3 significantly ameliorated arthritis in rodents." (PMID 18706093, 2008). "TLRs and CXCL10 may provide a partial explanation to the potential association between CKS and gout, as the first was shown to upregulate an important TLR in gout, as well as an important chemokine to the development of arthritis." (PMID 33519292, 2020). "We also demonstrated that the inhibition of CXCL10 by statins could alleviate CHIKV arthritis." (PMID 33147869, 2020). "Reference mapping showed that the majority of ICI-arthritis myeloid cells mapped onto four RA myeloid clusters: IL1B + FCN1 + HBEGF+, STAT1+ CXCL10+, SPP1+, and MERTK+ HBEGF+ clusters." (PMID 40662950, 2025). "These inflammatory markers also correlate with SLEDAI-2K, levels of dsDNA (CCL2, CXCL10), the presence of lupus nephritis (CCL2, CXCL10, and TNF-α), and arthritis (IL6)." (PMID 38881906, 2024). "CXCL10 KO and CXCR3 KO in mice ameliorated arthritis in CAIA model by suppressing macrophage and T cell accumulation in arthritic joints." (PMID 36860872, 2023). "In animal models of arthritis tofacitinib treatment has led to decreased levels of circulating IL-6, IL-8, CCL2, and CXCL10." (PMID 36124688, 2022). "Taken together, these findings indicate that the sFasL–DR5 interaction promotes arthritis by regulating the CX3CL1–CX3CR1 axis, which increases CCL2, CCL3, and CXCL10 production by CX3CR1+ immune cells." (PMID 34223817, 2021). "We previously reported that C-X-C motif chemokine 10 (CXCL10; also called IP-10) has important roles in joint inflammation and bone destruction in arthritis." (PMID 28724396, 2017). "All of the analyzed chemokines (CXCL2, CXCL10, and CCL2) peaked at 24 hours after arthritis induction." (PMID 22676339, 2012). "CXCL10 remained elevated throughout the response, whereas CCL2 and CXCL2 had decreased to control levels again by day 14 after arthritis induction." (PMID 22676339, 2012). "Our data parallel previous reports of these two chemokines in other forms of arthritis, such as RA, in which levels of CCL3 and CXCL10 measured in SF were higher than those in serum." (PMID 16507178, 2006). "This study focuses upon three chemokines, namely CCL5, CXCL10 and CCL3, which are potential novel therapeutic targets in arthritis." (PMID 16507178, 2006). "The TLR4 activation-induced or CXCR3-mediated CXCL10 upregulation can exert important roles in arthritis progression through TLR4 and CXCR3, suggesting that it could form a positive feedback loop between CXCL10 and its receptors TLR4 and/or CXCR3." (PMID 28724396, 2017).
Arthritis (continued). "We have previously shown that patients with antibiotic-refractory arthritis have significantly higher levels of proinflammatory cytokines and chemokines in SF, particularly IFN-γ and the IFN-inducible chemokines CXCL9 and CXCL10, than patients with antibiotic-responsive arthritis." (PMID 24286535, 2013). "CXCL10 is considered the most crucial and potent chemokine in CXCR3-mediated chemotaxis, as it is highly upregulated and its expression robustly correlates with disease severity in inflammatory disorders such as IBD, MS, and arthritis." (PMID 22162719, 2012). "To determine the role of CXCL10 signaling in the development of arthritis, we used the CAIA model in mice lacking Cxcl10–/– and Cxcr3–/–." (PMID 28724396, 2017).
Stroke (44 papers, 2012 to 2025). Sudden impairment of blood flow to a part of the brain due to occlusion or rupture of an artery to the brain. "Clinical meta‐analyses and cohort datasets have demonstrated that elevated levels of Il6, Il1β, Cxcl2, and Cxcl10 are closely associated with poorer stroke prognosis." (PMID 40585759, 2025). "Given that Cxcl10 and Ccl2 have both been associated with stroke prognosis in humans, their increased expression in old mice compared with that in young mice is noteworthy." (PMID 40867143, 2025). "While previous studies have reported the induction of Cxcl10 and Ccl2 in stroke, the age-dependent enhancement of their induction is a novel finding of our study." (PMID 40867143, 2025). "Plasma CXCL8 and CXCL10 show potential as prognostic biomarkers for stroke outcomes and as therapeutic targets suitable for reverse translation." (PMID 38861234, 2025). "In conclusion, plasma CXCL8 and CXCL10 show potential as both prognostic biomarkers for stroke outcomes and therapeutic targets." (PMID 38861234, 2025). "Real-time quantitative PCR measurements suggested the prominent elevation of multiple pro-inflammatory cytokines and chemokines, including IL-1β, IL-6, TNF-α, CCL2, CXCL1, and CXCL10 after stroke." (PMID 35761277, 2022). "Previously, this laboratory demonstrated that LIF treatment significantly reduced splenic IFN-gamma and prevented the upregulation of CXCL10 after stroke." (PMID 33376583, 2020). "Stroke caused an increased release of cytokines/chemokines such as CCL and its ligands MCP-1/CCL2, IP-10/CXCL10, and RANTES/CCL5." (PMID 33177990, 2020). "Administration of antibodies to block the IFNγ/CXCL10 signaling yields a significant decrease in the infarct volume and prevents the reduction in spleen size at 72 h after stroke." (PMID 33376583, 2020). "Previously, this lab demonstrated that LIF prevents the stroke-mediated increase in splenic CXCL10 at 72 h after stroke." (PMID 33376583, 2020). "CXCL10 is associated with increased infiltration of immune cells across the blood-brain barrier and is highly expressed in EAE and stroke." (PMID 31665042, 2019). "CXCL10 has been shown to be important in central leukocyte recruitment in stroke models, particularly in ischaemic cortex, with elevated levels also seen in a variety of other diseases." (PMID 25994490, 2015). "Ischaemic stroke models and peripheral IL-1 administration have been shown to increase levels of CXCL10/interferon-inducible protein-10 in unstimulated splenocytes, activating its receptor CXCR3." (PMID 25994490, 2015). "While CXCL10 is induced in the infarct region after stroke (which is consistent with our findings), its suppression has been shown to improve synaptic function and sensorimotor outcomes in the photothrombotic stroke model." (PMID 40867143, 2025). "However, when adjusting for factors like age, atrial fibrillation, NIHSS score on admission, and pre-stroke dependency in the multivariate analysis, only CXCL10 remained as an independent outcome predictor." (PMID 38861234, 2025). "However, after adjusting for age, hypertension, atrial fibrillation, NIHSS admission score, right-sided lesion, and pre-stroke dependency in a multivariate analysis, only higher levels of CXCL10, CXCL9, and CXCL8 remained independent predictors of outcome." (PMID 38861234, 2025). "M1 phenotype microglia can produce a variety of mediators, including inducible nitric oxide synthase (Nos2), C-X-C motif chemokine 10 (Cxcl10, as known as IP10), tumor necrosis factor (Tnfα), and cyclooxygenase-2 (Cox2) to induce oxidative stress, inflammation, and necroptosis after stroke." (PMID 34457033, 2021). "Also, LIF treatment promotes anti-inflammatory signaling by decreasing splenic levels of IFNγ and preventing the upregulation of CXCL10 that occurs after stroke." (PMID 33376583, 2020).